SUSD2 (sushi domain containing 2)
Diseases named in the same sentence as SUSD2 in open-access papers (continued):
Sharing a sentence is not in itself a finding about the gene and the disease.
gastric cancer (4 papers, 2018 to 2024). A primary or metastatic malignant neoplasm involving the stomach. "We chose to pursue a study of SUSD2 for the reasons as follows: (a) association with gastric cancer progression (SUSD2 is a membrane protein that may mediate interactions between cells and between cells and cell‐matrix adhesion molecules)." (PMID 30259711, 2018). "Shorter disease-free and overall survival are more likely to occur in hepatic recurrence of gastric cancer that shows high expression of SUSD2." (PMID 38206646, 2024). "The knockdown of SUSD2 in gastric cancer cell lines can attenuate cell growth, invasion, and migration rates." (PMID 39791720, 2024). "High SUSD2 expression was significantly correlated with shorter survival in patients with gastric cancer." (PMID 32194777, 2020). "In gastric cancer, Umeda S found that knockdown of SUSD2 could significantly reduce the proliferation, migration, and invasiveness of gastric cancer cells." (PMID 32194777, 2020).
glioma (4 papers, 2020 to 2023). A benign or malignant brain and spinal cord tumor that arises from glial cells (astrocytes, oligodendrocytes, ependymal cells). "For instance, circHECTD1 contributes to glioma progression by regulating the miR-296-3p/SLC10A7 axis, and circ-TOP2A regulates glioma progression via miR-346/SUSD2." (PMID 37575469, 2023). "In case of young age groups, there are some genes implicated to other cancers whose role in glioma has to be elucidated, yet, like AHNAK2 and SUSD2." (PMID 33639927, 2021).
lung adenocarcinoma (4 papers, 2020 to 2024). A carcinoma that arises from the lung and is characterized by the presence of malignant glandular epithelial cells. "SUSD2 (Sushi Domain Containing 2) was indicated to serve as a new prognostic and potential therapeutic target in lung adenocarcinoma." (PMID 37190150, 2023). "Additionally, lung adenocarcinoma patients with low SUSD2 expression levels have shorter survival, so SUSD2 may function as an independent prognostic indicator." (PMID 36619866, 2022). "There is limited evidence regarding the relationship between the expression of Sushi Domain Containing 2 (SUSD2) and prognosis of patients with surgically resected lung adenocarcinoma (LUAD)." (PMID 32194777, 2020).
breast tumor (3 papers, 2017 to 2024). "Immunohistochemical analysis has revealed that SUSD2 levels are correlated with an increased presence of M2-polarized tumor-associated macrophages (TAMs), which have tumor-promoting functions in human breast tumor tissues." (PMID 39791720, 2024). "Previous work has shown that 80% of patient breast tumors have moderate to high staining for SUSD2, and healthy tissues have minimal SUSD2 staining." (PMID 31387209, 2019). "Consistent with our previous analysis, 80% of the 175 evaluated breast tumors had moderate to strong staining for SUSD2 (2+/ 3+ composite score)." (PMID 28475599, 2017).
endometrial carcinoma (3 papers, 2017 to 2020). A malignant tumor arising from the epithelium that lines the cavity of the uterine body. "Our observations reveal that SUSD2 participates in the regulation of apoptosis and senescence in endometrial cancer cells." (PMID 28841682, 2017). "Taken together these findings suggest that SUSD2 is a potential chemotherapeutic target in human endometrial cancer." (PMID 28841682, 2017). "Treatment of endometrial cancer cells (Ishikawa cells) with TGFβ (10 ng/ml) significantly decreased SUSD2 transcript levels and the proportion of SUSD2 positive cells." (PMID 28841682, 2017). "Our present observations confirm that SUSD2 is present in endometrial cancer cells and that SUSD2 expression is sensitive to TGFβ signaling." (PMID 28841682, 2017). "In summary, we show that SUSD2 is present in endometrial carcinoma cells." (PMID 28841682, 2017). "Treatment of endometrial carcinoma cells with TGFβ reduced the expression of SUSD2." (PMID 28841682, 2017). "The present study explored whether the MSC marker SUSD2 is sensitive to TGFβ in human endometrial cancer (Ishikawa; well differentiated adenocarcinoma) cells." (PMID 28841682, 2017). "Whether, the role of SUSD2 and TGFβ signalling via SMADs in endometrial cancer cells remained to be defined." (PMID 28841682, 2017).
endometriosis (3 papers, 2021 to 2023). The growth of functional endometrial tissue in anatomic sites outside the uterine body. "Sampson's theory of endometriosis has now been extended to include endometrial stem/progenitor cells which have been found in menstrual fluid as N‐Cadherin+ cells and SUSD2+ eMSC." (PMID 36746607, 2023). "Inhibition of the activin A pathway prevents the myofibroblast differentiation of SUSD2+ eMSCs and improves fibrosis in endometriosis mice." (PMID 34425902, 2021). "In stromal endometriosis, SUSD2+ eMSC in menstrual fragments containing niche cells may attach and initiate stromal endometriosis lesions when shed into the pelvic cavity." (PMID 36746607, 2023). "Among these cytokines, activin A is significantly increased in PF from endometriosis group, whereas ALK4 (activin A-specific receptor) is increased in ectopic endometrial-derived SUSD2+ eMSCs." (PMID 34425902, 2021). "The concentration of SUSD2+ eMSC and N-cadherin+ eEPC in uterine menstrual blood appears similar between women with and without endometriosis." (PMID 36304009, 2021). "We identified clonogenic endometrial cells, SUSD2+ eMSC and N-cadherin+ eEPC concurrently in menstrual fluid and peritoneal fluid of women with and without endometriosis and also clonogenic endometrial cells and SSEA-1+ eEPC in menstrual fluid of normal women." (PMID 36304009, 2021).
endometrial adenocarcinoma (2 papers, 2017 to 2024). "The present study addressed the effect of TGFβ on MSCs marker SUSD2 in Ishikawa cells, a well differentiated endometrial adenocarcinoma cell line." (PMID 28841682, 2017).
Infertility (2 papers, 2021 to 2022). "In accordance with such fundamental functions, there is ample evidence for a role of SUSD2 in the etiology of infertility, although restricted to females to date." (PMID 36613967, 2022). "However, our study revealed that MenSCs obtained from patients with unexplained infertility are different from MenSCs from healthy volunteers in more pronounced expression of mesenchymal cell surface markers CD56, SUSD2." (PMID 34202508, 2021).
lymph node metastasis (2 papers, 2020 to 2024). "In LUAD patients with lymph node metastasis, high SUSD2 expression was also associated with better OS (P = 0.001)." (PMID 32194777, 2020). "Reduced SUSD2 expression was associated with gender, smoking history, higher pathological grade, lymph node metastasis, larger tumor length, advanced TNM stage." (PMID 32194777, 2020). "In the univariate analysis, the results showed that age, gender, smoking history, tumor length, T stage, lymph node metastasis, TNM stage and SUSD2 expression were associated with the OS of LUAD patients (all P < 0.05)." (PMID 32194777, 2020). "In patients without lymph node metastasis, high SUSD2 expression was associated with improved OS (P = 0.000)." (PMID 32194777, 2020). "In patients without lymph node metastasis, high SUSD2 expression was associated with improved OS (P = 0.013)." (PMID 32194777, 2020). "Age, smoking history, tumor length, lymph node metastasis, TNM stage and SUSD2 expression were independent prognostic factors of OS for LUAD patients (all P < 0.05)." (PMID 32194777, 2020). "Similarly, the basal level of SUSD2 is decreased in NSCLC tissues and inversely correlated with clinical stage and lymph node metastasis in NSCLC." (PMID 39791720, 2024). "The OS of patients with positive SUSD2 expression was significantly better in patients with stage I (P = 0.000), III (P = 0.000), without (P = 0.000) and with (P = 0.001) lymph node metastasis." (PMID 32194777, 2020).
retinoblastoma (2 papers, 2022 to 2024). A malignant tumor that originates in the nuclear layer of the retina. "They used the Gene Expression Omnibus (GEO) datasets, to identify the expression levels of SUSD2 and miR-141-3p in retinoblastoma samples compared to healthy controls." (PMID 36619866, 2022). "They concluded that SUSD2 acts as a RB tumor suppressor, and the miR-141-3p/SUSD2 axis could regulate both retinoblastoma development and angiogenesis, making it a new target for RB treatment." (PMID 36619866, 2022).
bladder cancer (1 paper, 2024). "Tumor Immune Estimation Resource analysis indicated that expression of SUSD2 was significantly associated with macrophage infiltration and M2 macrophage polarization in bladder cancer." (PMID 39247587, 2024). "In addition to analyzing public databases, we conducted IHC analysis and discovered significant SUSD2 overexpression in bladder cancer, with high levels associated with poor pathological stages." (PMID 39247587, 2024). "Despite these findings, the clinical value and biological role of SUSD2 in bladder cancer remain to be elucidated." (PMID 39247587, 2024). "Future studies should include bladder cancer specimens from diverse ethnic groups to verify SUSD2 expression levels and address the limitations of this research." (PMID 39247587, 2024). "We explored the biological function of SUSD2 in bladder cancer, particularly its effects on cell growth and motility." (PMID 39247587, 2024). "Multivariate Cox regression analysis revealed that the expression of SUSD2 served as an independent predictor of poor OS (adjusted hazard ratio = 1.53, 95% confidence interval = 1.01-2.31, p = 0.006) in the patients with bladder cancer." (PMID 39247587, 2024). "To determine the protein levels of SUSD2 in patients with bladder cancer, we analyzed the expression of SUSD2 in tumors from 189 patients by using immunohistochemistry and correlated these levels with clinicopathological features." (PMID 39247587, 2024). "The expression of SUSD2 was significantly higher in bladder cancer tissues than in normal bladder tissues (p = 0.035)." (PMID 39247587, 2024). "In summary, this study provides novel insights into how the miR-383-5p/SUSD2 axis influences the prognosis of bladder cancer by modulating cancer cell growth, metastasis, and the tumor microenvironment." (PMID 39247587, 2024). "Because immune checkpoint inhibitors play a key role in the treatment of bladder cancer 8, understanding the immunosuppressive role of SUSD2 within the tumor microenvironment is essential." (PMID 39247587, 2024). "In this study, we identified miR-383-5p as a miRNA capable of interacting with the 3'UTR of SUSD2 and to thus serve as a tumor suppressor in bladder cancer." (PMID 39247587, 2024). "The results indicated that the SUSD2 mRNA levels were significantly higher in bladder cancer tissues than in adjacent normal tissues (p < 0.001)." (PMID 39247587, 2024). "In summary, SUSD2 upregulation in bladder cancer is associated with advanced pathological stages, indicating a potential role for SUSD2 in the progression or cell motility of bladder cancer." (PMID 39247587, 2024). "To determine the effect of SUSD2 silencing on the migration, invasion, colony formation, and proliferation of bladder cancer cells, we first analyzed SUSD2 expression." (PMID 39247587, 2024). "This suggests that SUSD2 upregulation in bladder cancer, compared to corresponding adjacent normal tissues, is consistent regardless of cohort differences." (PMID 39247587, 2024). "Overall, this study highlights the potential importance of the miR-383-5p/SUSD2 axis in determining the prognosis of bladder cancer by modulating cancer cell growth and metastasis." (PMID 39247587, 2024). "High SUSD2 expression also positively correlated with M2 macrophage polarization in bladder cancer, indicating involvement of SUSD2 in the tumor microenvironment through macrophage recruitment and M2 polarization." (PMID 39247587, 2024). "Analysis of The Cancer Genome Atlas revealed significantly higher expression of SUSD2 mRNA in bladder cancer tissues than in adjacent normal tissues." (PMID 39247587, 2024). "SUSD2 suppression significantly reduced the proliferation, colony formation, and invasion of bladder cancer cells." (PMID 39247587, 2024). "In conclusion, this study provides novel insights into how the miR-383-5p/SUSD2 axis influences the prognosis of bladder cancer by modulating cancer cell growth, metastasis, and the tumor microenvironment." (PMID 39247587, 2024).
bladder cancer (continued). "Our findings indicate that silencing SUSD2 significantly reduces bladder cancer cell proliferation and colony formation by disrupting cell cycle progression and motility." (PMID 39247587, 2024). "We also investigated the correlation between SUSD2 mRNA expression and overall survival (OS) in patients with bladder cancer." (PMID 39247587, 2024). "Therefore, further research is required to fully elucidate the mechanism of action of SUSD2 in bladder cancer." (PMID 39247587, 2024). "Although the specific role of SUSD2 in the tumor microenvironment of bladder cancer remains unclear, its influence on macrophage polarization can be considered in the development of innovative therapeutic strategies." (PMID 39247587, 2024). "Our study revealed that miR-383-5p/SUSD2 axis dysfunction may contribute to a poor prognosis for bladder cancer by affecting cell growth, metastasis, and the tumor microenvironment." (PMID 39247587, 2024). "Although Sushi Domain Containing 2 (SUSD2) dysfunction has been identified in several types of human cancer, its biological role in bladder cancer remains unclear." (PMID 39247587, 2024). "In summary, dysfunction of the miR-383-5p/SUSD2 axis may contribute to a poor prognosis for bladder cancer because it may affect the growth and metastasis of bladder cancer cells." (PMID 39247587, 2024). "In addition, cell cycle analysis revealed that SUSD2 knockdown induced G2/M phase arrestin bladder cancer cells." (PMID 39247587, 2024). "Additionally, we presented evidence of a potential link between high SUSD2 expression and advanced disease stage in patients with bladder cancer." (PMID 39247587, 2024). "To determine the clinical effect of SUSD2 on bladder cancer, we analyzed data from TCGA." (PMID 39247587, 2024). "Clinical evidence indicates that SUSD2 is involved in the progression of bladder cancer." (PMID 39247587, 2024). "In addition, miR-383-5p directly targeted the 3'UTR of SUSD2, with its ectopic expression inhibiting the growth and motility of bladder cancer cells." (PMID 39247587, 2024). "Taken together, our findings indicate that the dysfunction of the miR-383-5p/SUSD2 axis may contribute to the poor prognosis of bladder cancer by affecting cancer cell growth and metastasis." (PMID 39247587, 2024). "In this study, we observed a significant correlation between high SUSD2 expression and increased macrophage infiltration in bladder cancer, indicating that SUSD2 may play a role in macrophage polarization toward the M2 phenotype, which supports tumor growth, angiogenesis, and metastasis." (PMID 39247587, 2024). "However, the clinical effect and biological function of SUSD2 in bladder cancer remain unknown." (PMID 39247587, 2024). "Further analysis showed that there was no significant negative correlation between miR-383-5p and SUSD2 mRNA expression in bladder cancer tissues." (PMID 39247587, 2024).
bladder urothelial carcinoma (1 paper, 2024). "Analysis of SUSD2 expression across various types of cancer revealed significant upregulation of SUSD2 in bladder urothelial carcinoma, breast invasive carcinoma, cholangiocarcinoma, head and neck squamous cell carcinoma, liver hepatocellular carcinoma, and thyroid carcinoma." (PMID 39247587, 2024).
clear-cell carcinoma (1 paper, 2016). "With the exception of clear-cell carcinoma, patient tissue samples of dysgerminoma and all subtypes of ovarian adenocarcinomas displayed positive SUSD2 epithelial cell staining." (PMID 27775699, 2016).
endometrial tumors (1 paper, 2021). "The double labelling with anti-SUSD2 and anti-NTPDase2 confirmed the perivascular colocalization of these two proteins in endometrial tumors." (PMID 33922226, 2021).
microtia (1 paper, 2023). "However, the molecular mechanism underlying microtia or CHD and SUSD2 remains unknown, and further studies will be required to address this issue." (PMID 37107637, 2023).
ovarian tumors (1 paper, 2016). "Surprisingly, immunohistochemical (IHC) analysis revealed that HGSOC patients with high levels of SUSD2 staining in their primary ovarian tumors have a better prognosis compared with patients with low levels of SUSD2 staining." (PMID 27775699, 2016).
psoriasis (1 paper, 2022). An autoimmune condition characterized by red, well-delineated plaques with silvery scales that are usually on the extensor surfaces and scalp. "In addition, other studies reported that C10orf99 displays DAMP activity and is a ligand for sushi domain containing 2 (SUSD2) and was suggested to play a role in psoriasis pathogenesis." (PMID 35704588, 2022).
squamous cell carcinoma (1 paper, 2024). A carcinoma arising from squamous epithelial cells. "Stratification analysis revealed a significant increase in SUSD2 expression in both urothelial carcinoma (p = 0.039) and squamous cell carcinoma (p < 0.001) relative to that in normal tissues." (PMID 39247587, 2024).